IMPDH2 (inosine monophosphate dehydrogenase 2)
Description:
Catalyzes the conversion of inosine 5'-phosphate (IMP) to xanthosine 5'-phosphate (XMP), the first committed and rate-limiting step in the de novo synthesis of guanine nucleotides, and therefore plays an important role in the regulation of cell growth. Could also have a single-stranded nucleic acid-binding activity and could play a role in RNA and/or DNA metabolism. It may also have a role in the development of malignancy and the growth progression of some tumors.
Synonyms: IMPDH-II; IMPD2
Tractability: Small molecule: an approved drug acts on it; a structure with a bound ligand is known; a high-quality ligand is known; it has a high-quality binding pocket; it belongs to a druggable protein family. Antibody: its Gene Ontology location is reachable by antibodies, with high confidence. PROTAC: UniProt records ubiquitination sites on it; ubiquitination databases record sites on it; its protein half-life has been measured; a small molecule that binds it is known.
Target class: Enzyme; Oxidoreductase
Chemical probes: BMS 566419, PD081382, PD081955, PD085080
Safety:
Unwanted effects reported when the protein is acted on. In parentheses: how it was acted on, where the effect was seen, and who reports it.
acute rejection (source: ClinPGx)
acute rejection after kidney transplantation (source: ClinPGx)
incidence of lymphopenia (source: ClinPGx)
Gene: Protein-coding gene on chromosome 3 (49,024,321 to 49,029,452, reverse strand). Ensembl gene ENSG00000178035.
Subcellular location: Cytoplasm; Nucleus; Cytoplasm, cytosol
Subcellular location (Human Protein Atlas): Cytosol; Rods & Rings
Pathways (Reactome):
Disease: Potential therapeutics for SARS
Drug ADME: Azathioprine ADME
Immune System: Neutrophil degranulation
Metabolism: Purine ribonucleoside monophosphate biosynthesis
Gene Ontology:
Molecular function: IMP dehydrogenase activity; nucleotide binding; protein binding; catalytic activity; metal ion binding; oxidoreductase activity
Biological process: circadian rhythm; GTP biosynthetic process; 'de novo' XMP biosynthetic process; GMP biosynthetic process; purine nucleotide biosynthetic process
Cellular component: cytoplasm; cytosol; extracellular exosome; membrane; nucleus; peroxisomal membrane; extracellular region; ficolin-1-rich granule lumen; secretory granule lumen
Genetic constraint (gnomAD): Loss-of-function variants: 33 observed, 57.61 expected, observed/expected ratio (o/e) 0.57, 90% interval 0.43 to 0.77. The upper end of that interval is the gene's LOEUF score, 0.77, which puts it in group 3 of 6, group 1 being the genes least tolerant of losing a copy. Missense variants: 445 observed, 681.71 expected, observed/expected ratio (o/e) 0.65, 90% interval 0.6 to 0.71. Synonymous variants: 270 observed, 252.91 expected, observed/expected ratio (o/e) 1.07, 90% interval 0.97 to 1.18.
Homologues: Orthologues: chimpanzee IMPDH2 (100% identical), dog IMPDH2 (99% identical), guinea pig IMPDH2 (99% identical), macaque IMPDH2 (99% identical), pig IMPDH2 (99% identical), mouse Impdh2 (99% identical), rat Impdh2 (98% identical), tropical clawed frog impdh2 (93% identical), zebrafish impdh2 (91% identical), rabbit IMPDH2 (91% identical). Paralogues in human: IMPDH1 (83% identical), GMPR (20% identical), GMPR2 (20% identical).
Diseases named in the same sentence as IMPDH2 in open-access papers:
IMPDH2 is named in the same sentence as 90 diseases in open-access papers, as found by Europe PMC text mining. Sharing a sentence is not in itself a finding about the gene and the disease. The quoted sentences say what the papers report.
colorectal cancer (10 papers, 2015 to 2025). A primary or metastatic malignant neoplasm that affects the colon or rectum. "Duan and colleagues found that the PI3K/ATK/mTOR pathway was related to invasion, migration, and proliferation of colorectal cancer induced by IMPDH2." (PMID 30870998, 2019). "Similarly, inosine monophosphate dehydrogenase 2 (IMPDH2), a key enzyme in purine biosynthesis, is upregulated in cancers, promoting pro-tumorigenic phenotypes and chemotherapy resistance in glioblastoma, colorectal cancer, and triple-negative breast cancer." (PMID 40734168, 2025). "However, the clinical significance and biological role of IMPDH2 remain poorly understood in colorectal cancer (CRC)." (PMID 30518405, 2018). "However, IMPDH2 has been tested as a potential biomarker using IHC in colorectal cancer and appears to be a promising target for both detection and treatment." (PMID 25869206, 2015). "Chemoresistance to 5-FU in colorectal cancer has been shown to be induced by B7-H3 through enhanced PI3K/AKT signalling, but the role of IMPDH2 in this system has not been explored." (PMID 37444640, 2023).
Dystonia (7 papers, 2021 to 2025). An abnormally increased muscular tone that causes fixed abnormal postures. "Several point mutations in the IMPDH2 gene have been described in patients with dystonia and other neurodevelopmental disorders." (PMID 40710358, 2025). "Two additional rare co‐segregating IMPDH2 variants were uncovered in a screening of patients with adult‐onset isolated dystonia, but their disease‐causing nature remains to be proven." (PMID 40026236, 2025). "In 2020, a large‐scale genomic study that integrated global matchmaking for rare‐disease cases reported on the discovery of autosomal dominant heterozygous variants in IMPDH2, encoded by IMPDH2, in patients with dystonia." (PMID 40026236, 2025). "Such shifts in pathway utilization would be the expected outcome of several purine‐pathway enzyme defects resulting in PMDs, including LND and, potentially, IMPDH2‐related dystonia caused by gain‐of‐function mutations." (PMID 40026236, 2025). "The frameshift IMPDH2 variant discovered in a large dystonia‐tremor family was shown to exert an opposite effect on IMPDH2 function." (PMID 40026236, 2025). "The recent discovery of gain‐of‐function IMPDH2 pathogenic variants in patients with prominent dystonic manifestations provides new insights into the link between dystonia and purinergic system defects." (PMID 40026236, 2025). "A dominant mutation of Impdh2 has recently been associated with dystonia linked with dopamine biosynthesis." (PMID 37958822, 2023). "Five mutations in IMPDH2 were recently identified in patients with early onset neurodevelopmental diseases, including dystonia." (PMID 37414152, 2023). "Multiple point mutations in the human isoform IMPDH2 have recently been associated with dystonia and other neurodevelopmental disorders, but the effect of the mutations on enzyme function has not been described." (PMID 37414152, 2023). "Rare variants of IMPDH2 affecting the catalytic domain have also been identified in a cohort of dystonia patients of Chinese ancestry." (PMID 37414152, 2023). "IMPDH2 deficiency is characterized by dystonia and tremor, and its onset has been evaluated between 9 and 20 years of age." (PMID 37512494, 2023). "Whole-exome sequence analysis was employed for the recent identification of IMPDH2 variants in dystonia-affected individuals and in a Finnish family affected by juvenile-onset dystonia-tremor disorder." (PMID 37512494, 2023). "Recent studies have identified mutations in inosine 5′ monophosphate dehydrogenase (IMPDH) 2, a key regulatory enzyme in purine nucleotide biosynthesis, associated with dystonia and other neurodevelopmental disorders." (PMID 37414152, 2023). "Clinically, IMPDH2-linked dystonia mimicks other dominantly inherited dystonias such as those caused by variants in GCH1, also an enzyme in the GTP-BH4 pathway." (PMID 34305140, 2021). "Here we report a deleterious heterozygous truncating variant in the inosine monophosphate dehydrogenase gene (IMPDH2) by whole-exome sequencing, co-segregating with a dominantly inherited dystonia-tremor disease in a large Finnish family." (PMID 34305140, 2021). "The IMPDH2 reaction is flanked by HPRT1 products—also a dystonia-linked protein—upstream from GCH1." (PMID 34305140, 2021). "In conclusion, IMPDH2 is a novel dystonia gene linked to the dopamine synthesis pathway, implying that the symptoms may be L-DOPA responsive." (PMID 34305140, 2021). "Therefore, the emerging dominant gain‐of‐function paradigm for IMPDH2‐related dystonia could offer clues to better understand disease‐associated molecular drivers and ultimately pathogenesis." (PMID 40026236, 2025). "However, more recently, a heterozygous early termination in exon 1 of IMPDH2 was identified in a patient with dystonia, suggesting a decrease in IMPDH2 activity could also be causative of disease." (PMID 37414152, 2023).
Dystonia (continued). "Only recently, a growing body of evidence highlighted a causal relationship between both gain‐ and loss‐of‐function variants in 1 key enzyme of the purine de novo synthetic pathway, inosine‐5‐prime‐monophosphate dehydrogenase type 2 (IMPDH2), and dystonia." (PMID 40026236, 2025). "Glial dysfunction is an increasingly appreciated contributor to dystonia pathogenesis, highlighting studies into the role of abnormal astrocytogenesis in IMPDH2‐related dystonia as a promising future research topic." (PMID 40026236, 2025). "We discuss here 3 such relationships, supported by available evidence from LND, IMPDH2‐related dystonia and other PMDs, as well as animal or cellular models." (PMID 40026236, 2025). "The recent discovery of IMPDH2‐related dystonia introduced a gain‐of‐function paradigm in purinergic system defects, offering new perspectives to understand purine‐pool imbalances in brain diseases." (PMID 40026236, 2025). "The characterization of IMPDH2 as a new disease gene enhances our knowledge about the relationship between purine metabolism abnormalities and dystonia." (PMID 40026236, 2025). "Moreover, the described association of a loss‐of‐function IMPDH2 variant with dystonia emphasizes a more complex scenario, in which both genetically mediated increases and decreases in guanine and adenine nucleotide levels could be related to disease evolution." (PMID 40026236, 2025). "As such, IMPDH2‐related disease may serve as a useful novel model to study neurodevelopmental versus neurodegenerative mechanisms in dystonia." (PMID 40026236, 2025). "In this review, we discuss how knowledge of the role of dystonic features in PMDs is expanding, especially because of the discovery of IMPDH2‐related dystonia, and how the new observations can help to redefine the role of purine metabolism aberrations in dystonia etiology." (PMID 40026236, 2025). "Although the precise mechanisms of neurodevelopmental dysfunction in IMPDH2‐related dystonia remain largely unexplored, preliminary evidence from Toyoda and colleagues indicates that IMPDH2 filaments are enriched during development in the distal ends and branching sites of astrocytes." (PMID 40026236, 2025). "Moreover, insights from IMPDH2‐related disease can help to better understand which type(s) of purine metabolism imbalance(s) is (are) more likely to result in dystonia." (PMID 40026236, 2025). "We report IMPDH2 as a new gene to the dystonia disease entity." (PMID 34305140, 2021). "Furthermore, a recent large study focusing on neurodevelopmental disorders with dystonia raised attention to IMPDH2 as a candidate gene, but direct evidence has been lacking." (PMID 34305140, 2021). "We propose that in post-mitotic cells of the CNS, with considerably lower nucleotide pools than in cultured fibroblasts and high IMPDH2 expression, the enzyme defect becomes rate-limiting, challenging guanine and dopamine synthesis and resulting in dystonia and tremor." (PMID 34305140, 2021). "Moreover, IMPDH2‐mutated patients have been identified who demonstrated neurodevelopmental syndromes without any signs of dystonia at the time of last examination, highlighting a notable degree of variable expressivity for the condition." (PMID 40026236, 2025).
glioblastoma (7 papers, 2021 to 2025). The most malignant astrocytic tumor (WHO grade IV). "IMPDH2 is over-expressed in a range of cancers including glioblastoma, where its elevated levels drive increased synthesis of rRNA and tRNA, stabilization of the GTP-binding nucleolar protein nucleostemin and nucleolar hypertrophy." (PMID 40367275, 2025). "In glioblastoma, IMPDH2 amplifies rRNA and tRNA synthesis, fostering accelerated cell proliferation." (PMID 39085725, 2024). "In a glioblastoma model, an increased GTP level due to IMPDH2 induction in cancer cells caused the transcriptional activation of ribosomal RNAs, thereby increasing ribosomal biogenesis, upregulating cellular genes, and promoting cellular proliferation." (PMID 37409959, 2023). "Although the significance of IMPDH2 induction and nuclear hypertrophy in the tumorigenesis of glioblastoma has been reported, EBV infection brings about the change quickly by using its transcriptional cofactor, EBNA2, and MYC." (PMID 37409959, 2023). "Consistently, clinical trials are currently underway in glioblastoma multiforme (NCT04477200, NCT05236036) to evaluate the combination of mycophenolate mofetil (MMF, a prodrug form of the IMPDH2 inhibitor MPA, possessing better bioavailability) with temozolomide and/or radiation." (PMID 39774345, 2025).
melanoma (7 papers, 2014 to 2024). A malignant, usually aggressive tumor composed of atypical, neoplastic melanocytes. "In addition, it has been demonstrated that c-Myc plays a critical role in the maintenance of expression of PRPS2, PPAT, TrifGART, PAICS and IMPDH2 in melanoma cells and of PPAT, IMPDH1, IMPDH2 but not PAICS in a human lymphoma model cell line." (PMID 38444943, 2024). "Because MYC reportedly induces IMPDH2 in melanoma, we used a specific inhibitor of MYC (10058-F4)." (PMID 37409959, 2023). "ROH island analyses identified several annotated genes (SPRY4, NDFIP1, HSP90AB1 and IMPDH2), which may play a role for further studies on equine melanoma." (PMID 30836959, 2019). "By means of ROH island analyses, we identified the genes SPRY4, NDFIP1, IMPDH2, HSP90AB1, which might play an important role for further studies on equine melanoma." (PMID 30836959, 2019).
osteosarcoma (7 papers, 2010 to 2023). A usually aggressive malignant bone-forming mesenchymal neoplasm, predominantly affecting adolescents and young adults. "Higher IMPDH2 expression in osteosarcoma is associated with a poor prognosis and even resistance to chemotherapy and radiotherapy." (PMID 37409959, 2023). "A later study also demonstrated an association between high IMPDH2 level and poor response to chemotherapy and low metastasis-free survival in osteosarcoma patients." (PMID 34035425, 2021). "Increased IMPDH2 expression in cancer cells has been linked to resistance to methotrexate in osteosarcoma, colorectal and erythroleukemia cells." (PMID 24941944, 2014). "Integrative analysis of IMPDH2 and HPRT will provide valuable data on an association of rewired GTP synthesis system in osteosarcoma and clinical outcomes of the patients." (PMID 34035425, 2021). "As Rb and IMPDH2 are related to the progression of osteosarcoma, siRNA transfection and a CCK-8 assay were performed for the functional screening of the other 9 nuclear proteins." (PMID 28460433, 2017). "On the other hand, overexpression of IMPDH2 induced a strong chemoresistance in osteosarcoma cells which was mediated partly by upregulation of anti-apoptotic proteins, leading to inhibition of the mitochondrial apoptotic signaling pathway." (PMID 28389646, 2017). "In fact, the findings of the present study demonstrate that overexpression of IMPDH2 in osteosarcoma cells induces strong chemoresistance to cisplatin and methotrexate, two drugs frequently used for osteosarcoma therapy." (PMID 20808934, 2010). "In a previous study we identified IMPDH2 as an independent prognostic factor and observed frequent IMPDH2 overexpression in osteosarcoma patients with poor response to chemotherapy." (PMID 20808934, 2010). "Our results demonstrate that IMPDH2 overexpression induces a strong chemoresistance in osteosarcoma cells which is mediated at least in part by increased expression of anti-apoptotic proteins." (PMID 20808934, 2010). "In a previous study we identified IMPDH2 (inosine monophosphate dehydrogenase, type II) as independent prognostic factor for the response to chemotherapy in osteosarcoma patients." (PMID 20808934, 2010). "We further screened osteosarcoma biopsies for IMPDH2 gene expression and correlated these data with the patients' response to chemotherapy as well as their overall and event-free survival." (PMID 20808934, 2010). "Stable cell lines overexpressing IMPDH2 and IMPDH2 knock-down cells were generated using the osteosarcoma cell line Saos-2 as parental cell line." (PMID 20808934, 2010). "The aim of the present study was to investigate whether IMPDH2 is directly involved in the development of chemoresistance in osteosarcomas and whether inhibition of IMPDH2 activity or gene expression might usefully improve the outcome of therapy." (PMID 20808934, 2010). "However, the result from multivariate analysis revealed a significant association between HPRT levels and survival rate of osteosarcoma patients, but not for IMPDH2 expression results." (PMID 34035425, 2021). "As IMPDH2 overexpression is frequently observed in osteosarcoma patients with poor response to chemotherapy, targeting of IMPDH2 by RNAi or more effective inhibitors in combination with chemotherapy might provide an effective synergistic treatment to overcome chemoresistance in osteosarcomas." (PMID 20808934, 2010). "To verify this hypothesis we established osteosarcoma cell lines with modulated IMPDH2 expression either by overexpression of the IMPDH2 coding sequence in Saos-2 cells (Saos-2 cdsIMPDH2) or by IMPDH2 knock-down using an shRNA construct specific for IMPDH2 (Saos-2 shIMPDH2)." (PMID 20808934, 2010). "To examine expression profiles and staining patterns of IMPDH2 and HPRT enzymes, we conducted immunohistochemical analysis of formalin-fixed paraffin-embedded tissues from biopsy samples of 127 osteosarcoma cases and 20 post-chemotherapy samples." (PMID 34035425, 2021).
osteosarcoma (continued). "In the present study, we investigated levels of IMPDH2, and HPRT in biopsy of 127 cases and post-chemotherapy tissues in 20 cases of high-grade osteosarcoma patients using immunohistochemical (IHC) analysis." (PMID 34035425, 2021). "We found IMPDH2 and HPRT expressed mainly in the cytosol of the osteosarcoma cells." (PMID 34035425, 2021). "Although IMPDH2 knock-down or pharmacological inhibition of IMPDH2 enzyme activity did not significantly influence the chemosensitivity of wild-type osteosarcoma cells, chemoresistant IMPDH2-overexpressing Saos-2 cells were resensitized by IMPDH2 knock-down." (PMID 20808934, 2010). "Profiling of IMPDH2 and hypoxanthine–guanine phosphoribosyltransferase (HPRT), key purine-metabolizing enzymes, could deepen understanding of the importance of purine metabolism in osteosarcoma and provide evidence for expanded use of MMF in the clinic." (PMID 34035425, 2021).
prostate carcinoma (7 papers, 2015 to 2026). A carcinoma that arises from epithelial cells of the prostate gland. "The eight proteins highlighted in this study (KLK3, SORD, SPON2, IMPDH2, ACTN4, ATP1B1, HSPB1, and KHDRBS1) represent a signature associated with AR modulation during the transition from androgen-dependent to castration-resistant prostate cancers." (PMID 29966326, 2018). "In prostate cancer stem cells (PCSCs), IMPA1 upregulation increases inositol levels, which directly bind and activate inosine monophosphate dehydrogenase 2 (IMPDH2), a key enzyme in purine biosynthesis." (PMID 40734168, 2025).